SERPINB4 (serpin family B member 4)
Description:
May act as a protease inhibitor to modulate the host immune response against tumor cells.
Synonyms: SCCA-2; PI11; SCCA2; LEUPIN; SCCA1
Tractability: Antibody: its Gene Ontology location is reachable by antibodies, with high confidence.
Gene: Protein-coding gene on chromosome 18 (63,637,259 to 63,644,256, reverse strand). Ensembl gene ENSG00000206073.
Subcellular location: Cytoplasm
Subcellular location (Human Protein Atlas): Cytosol; Plasma membrane
Gene Ontology:
Molecular function: enzyme binding; protease binding; protein binding; serine-type endopeptidase inhibitor activity; endopeptidase inhibitor activity
Biological process: protection from natural killer cell mediated cytotoxicity; regulation of proteolysis
Cellular component: cytosol; cytoplasm
Genetic constraint (gnomAD): Loss-of-function variants: 36 observed, 30.87 expected, observed/expected ratio (o/e) 1.17, 90% interval 0.89 to 1.54. The upper end of that interval is the gene's LOEUF score, 1.54, which puts it in group 6 of 6, group 1 being the genes least tolerant of losing a copy. Missense variants: 548 observed, 453.47 expected, observed/expected ratio (o/e) 1.21, 90% interval 1.13 to 1.3. Synonymous variants: 189 observed, 165.35 expected, observed/expected ratio (o/e) 1.14, 90% interval 1.01 to 1.29.
Homologues: Orthologues: chimpanzee SERPINB4 (97% identical), mouse Serpinb3a (61% identical), mouse Serpinb3d (60% identical), rat Serpinb3 (60% identical), mouse Serpinb3b (59% identical), rat Serpinb3a (58% identical), mouse Serpinb3c (57% identical), tropical clawed frog serpinb4 (43% identical). Paralogues in human: SERPINB3 (92% identical), SERPINB13 (58% identical), SERPINB1 (49% identical), SERPINB12 (49% identical), SERPINB6 (47% identical), SERPINB9 (46% identical), SERPINB10 (46% identical), SERPINB8 (44% identical), SERPINB11 (44% identical), SERPINB2 (43% identical), SERPINB7 (39% identical), SERPINC1 (38% identical), and 24 more.
Diseases named in the same sentence as SERPINB4 in open-access papers:
SERPINB4 is named in the same sentence as 56 diseases in open-access papers, as found by Europe PMC text mining. Sharing a sentence is not in itself a finding about the gene and the disease. The quoted sentences say what the papers report.
psoriasis (25 papers, 2014 to 2025). An autoimmune condition characterized by red, well-delineated plaques with silvery scales that are usually on the extensor surfaces and scalp. "In the data obtained in our previous study, we found that SERPINB4 expression was associated with increased psoriasis severity." (PMID 36999136, 2023). "Given that increased SERPINB4 expression was associated with psoriasis severity, we are committed to discussing its role in the pathogenesis of psoriasis." (PMID 36999136, 2023). "SERPINB4 has been previously associated with early inflammation in atopic dermatitis and psoriasis." (PMID 38542470, 2024). "Taken together, our results suggested that SERPINB4 may be implicated in the pathogenesis of psoriasis." (PMID 36999136, 2023). "Recent cutaneous transcriptomic studies in PN have revealed Th22 and Th17 immune gene signatures shared among PN, psoriasis, and atopic dermatitis (AD), including SERPINB4." (PMID 40995892, 2025). "SerpinB4-derived protein Pso p27, an autoantigen in psoriasis, increases inflammation and promotes migration of immune cells The increase in expression of SerpinB4 in the skin can promote inflammation, poor differentiation of keratinocyte." (PMID 39737188, 2024). "Taken together, these in vitro and in vivo results pointed toward a potential role of SERPINB4 in the pathogenesis of psoriasis." (PMID 36999136, 2023). "Elevated levels of the serine protease inhibitors SERPINB3 and SERPINB4 are seen in patients with atopic dermatitis and psoriasis, further clinical studies found that SERPINB4 is closely associated with the clinical severity of these two diseases." (PMID 36999136, 2023). "In this study, we found that SERPINB4 expression was upregulated in skin from IMQ-induced psoriasis-like mice as well as in M5-induced psoriasiform cell model." (PMID 36999136, 2023). "SERPINB4 expression was upregulated in skin lesions of IMQ-induced psoriasis-like mice and M5 induced psoriasiform cell model." (PMID 36999136, 2023). "Further, accumulating research has indicated that SERPINB4 is upregulated in many inflammatory skin diseases including psoriasis and atopic dermatitis, and serum SERPINB4 level is positively correlated with clinical severity of patients." (PMID 36999136, 2023). "In summary, SERPINB4 expression was upregulated in patients with psoriasis as well as in vivo and in vitro models of psoriasis." (PMID 36999136, 2023). "Top up-regulated DEGs in CP vs C include previously identified psoriasis-associated genes such as IL36A/G, SPRR2A/B/F, SERPINB4, S100A7A, S100A9, and IL17F while top down-regulated DEGs include SERTM1, IL6, and ADAMTS16." (PMID 30054515, 2018). "Examples of KC-assigned genes strongly elevated in psoriasis lesions included SERPINB4, SPRR2C and SERPINB3." (PMID 24885462, 2014). "Therefore, serum SERPINB4 level in psoriasis and AD is positively correlated with the clinical severity of patients and emerged as a useful biomarker indicating the severity of these patients." (PMID 40995892, 2025). "We revealed 479 differentially expressed genes between secukinumab and Dead Sea climatotherapy at the end of treatment, with a psoriasis panel identifying SERPINB4, SERPINB13, IL36G, IL36RN, and AKR1B10 as upregulated in Dead Sea climatotherapy compared with secukinumab." (PMID 38892277, 2024). "Our results showed that SERPINB4 may promote keratinocyte inflammation via activation of p38MAPK in psoriasis." (PMID 36999136, 2023). "We speculated that SERPINB4 may promote inflammation through p38MAPK pathway in the process of psoriasis-like inflammation." (PMID 36999136, 2023). "In this study, we first discovered that the expression of SERPINB4 was upregulated in skin lesions of IMQ-induced psoriasis-like mice and M5-induced psoriasiform cell model, and then examined the biological function of SERPINB4 by knockdown and overexpression approaches in vitro." (PMID 36999136, 2023).
psoriasis (continued). "Taken together, these results suggest that SERPINB4 has a critical role in psoriasis pathogenesis." (PMID 36999136, 2023). "However, the roles of SERPINB3 and SERPINB4 as antigens in psoriasis are controversial and require further investigation, especially SERPINB4, which was highly upregulated in the PE skin." (PMID 35563374, 2022). "Additionally, other studies also reported the increased expression of SERPINB4 gene in skin and serum of psoriasis patients." (PMID 34925353, 2021). "Using two-dimensional (2D) gel electrophoresis, an early study identified 21 skin proteins, including eight proteins with 2-fold increased abundance in psoriasis lesions (SERPINB4, GSTP1, SERPINB5, ARHGDIA, HSPB1, KRT14, KRT17, YWHAQ) and two others with 2-fold decreased abundance (KRT15, CALR)." (PMID 26251673, 2015). "How SERPINB4 regulates inflammation in M5-induced psoriasis-like keratinocyte is still unknown." (PMID 36999136, 2023). "In addition, the over-accumulation of abnormal SERPINB3 might increase the levels of Pso p27, an autoantigen derived from SERPINB3 and SERPINB4, which is highly involved in the inflammatory process in psoriasis." (PMID 36833193, 2023). "Some DEGs, however, are known to be involved in the pathogenesis of psoriasis (e.g., SERPINB3 and SERPINB4)." (PMID 38892277, 2024). "The core NB-UVB downregulated DEGs included a few psoriasis signature genes, such as IL36G, DEFB4A/B (coding human β defensin 2), S100A15, SERPINB4, KRT16, KRT6A, and DSC220." (PMID 36928592, 2023). "Thus targeting SERPINB4 may represent a potent strategy in psoriasis treatment." (PMID 36999136, 2023). "In conclusion, NB-UVB normalizes psoriatic plaques by suppressing the expression of psoriasis signature genes, such as IL36G, DEFB4A/B, S100A15, SERPINB4, KRT16, and KRT6A in, both, the PE and CE skin." (PMID 36928592, 2023). "These genes include genes that are well known to be involved in psoriasis, including LCE3D, LCE3E, SERPINB4, and S100A7A, genes involved in activation and proliferation of keratinocytes, modulation of host immune response, and antimicrobial defense." (PMID 30054515, 2018). "DEGPs provide a high-confidence molecular fingerprint of psoriasis and, as expected, we confirmed changes in mRNA and protein abundance for select DEGPs (FABP5 and SERPINB4) using RT-PCR and immunohistochemistry." (PMID 26251673, 2015). "IL-17 also induced a number of anti-microbial peptides, including S100A12, S100A7A, SERPINB4, SERBINB3, which are highly expressed in psoriasis, as has been described previously." (PMID 24587313, 2014). "SERPINB4, as a serine protease inhibitor, has been clearly expressed in the skin lesions and serum of patients with psoriasis, but the specific mechanism of action is not yet clear." (PMID 36999136, 2023). "The serpin-derived protein Pso p27, an autoantigen in psoriasis and other chronic inflammatory diseases, is proteolytically derived from SERPINB3 and SERPINB4 through non-canonical cleavage in mast cells by chymase." (PMID 36833193, 2023).
squamous cell carcinoma (9 papers, 2010 to 2025). A carcinoma arising from squamous epithelial cells. "SERPINB4 has been previously identified as associated gene with loci 18q deletion syndrome and squamous cell carcinoma." (PMID 35439935, 2022). "Moreover, elevated SERPINB4 levels in patients with squamous cell carcinomas are associated with an advanced stage of tumor progression and poor disease-free survival." (PMID 21857942, 2011). "Squamous cell carcinoma antigen (SCC-Ag, also called SCCA, with isoforms SCCA1/SERPINB3 and SCCA2/SERPINB4) is a glycoprotein first isolated from squamous carcinomas and is widely studied as a serum tumor marker in cervical squamous cell carcinoma." (PMID 41464230, 2025). "The squamous cell carcinoma antigenes SERPINB3 (SCCA1) and SERPINB4 (SCCA2) are circulating tumor markers for squamous cell carcinoma." (PMID 23285167, 2012). "Squamous cell carcinoma antigen 2 (SCCA2, SERPINB4), as one of the squamous cell carcinoma antigens, has been used as a tumor marker of some squamous cell carcinomas to predict the pathological grade, stage, recurrence, and response to radiotherapy and chemotherapy." (PMID 36999136, 2023). "Interestingly, tumors originating from these epithelial tissues also express SERPINB4, i.e. squamous cell carcinomas of the cervix, head and neck, and lung." (PMID 21857942, 2011). "As SERPINB4 is highly expressed by squamous cell carcinomas, our results may represent a novel mechanism by which these tumor cells evade cytotoxic lymphocyte-induced GrM-mediated cell death." (PMID 21857942, 2011).
melanoma (6 papers, 2020 to 2024). A malignant, usually aggressive tumor composed of atypical, neoplastic melanocytes. "Recently, somatic mutations in SERPINB4 and SERPINB3 (predominantly missense mutations) were described in melanoma, and were associated with improved survival after anti-CTLA4 immunotherapy." (PMID 35085295, 2022). "It has also been reported that SERPINB4 gene was deleted in all patients of malignant peripheral nerve sheath tumor-like melanoma, a rare malignancy melanoma, and may have a tumor suppressor activity." (PMID 35626221, 2022). "Another mutational event associated with response to ICIs in melanoma were mutations in SERPINB3 and SERPINB4, which might promote the formation of immunologically significant neoepitopes." (PMID 32969604, 2020).
asthma (5 papers, 2018 to 2023). "Serine protease inhibitors (SERPIN) genes like SERPINB2 and SERPINB4 have an important role in asthma pathogenesis." (PMID 32770056, 2020). "A recent study found 5 hub genes (SERPINB2, SERPINB4, LTF, MUC5B, and CST4) related to the pathogenesis of asthma in bronchial and nasal cells." (PMID 36076228, 2022).
allergic disease (4 papers, 2021 to 2022). An immune response that occurs following re-exposure to an innocuous antigen, and that requires the presence of existing antibodies against that antigen. "SERPINB3 and SERPINB4 in patients suffering from allergic disease control the viability of Th2 cells by exerting anti-apoptotic effects." (PMID 34126986, 2021). "Expression of several members in clade B, such as SERPINB2, SERPINB3 and SERPINB4, is upregulated in allergic diseases, and they modulate Th1/Th2 responses." (PMID 34126986, 2021). "SERPINB3 and SERPINB4 are upregulated in memory Th2 and innate helper 2 cells of allergy patients." (PMID 35626221, 2022).
inflammatory skin disease (4 papers, 2018 to 2023). Inflammatory skin disorders covers a broad category that includes many conditions ranging in severity, from mild itching to grave medical health complications These disorders are common in people of all ages and races. "SERPINB4 encodes squamous cell carcinoma antigen 2, a member of the serpin family that has serine protease inhibitor functions, and that was initially discovered as a tumor-specific antigen in uterine carcinomas and later described as a biomarker for inflammatory skin diseases." (PMID 35085295, 2022).
breast carcinoma (2 papers, 2022 to 2023). "SERPINB3/SERPINB4 has been found to be upregulated in a variety of cancer tissues, including esophageal cancer, cervical cancer, head and neck cancer, liver cancer, breast cancer, and so on." (PMID 36999136, 2023). "Importantly, the top 4 genes induced by OSM in CAF-173 (SERPINB4, THBS1, RARRES1, and TNC) are associated with decreased overall survival in breast cancer patients." (PMID 35192545, 2022).
Cirrhosis (2 papers, 2004 to 2012). A chronic disorder of the liver in which liver tissue becomes scarred and is partially replaced by regenerative nodules and fibrotic tissue resulting in loss of liver function. "SerpinB4-IgM median values obtained with SCC103 antibody were moderately higher in patients with cirrhosis than in those with HCC, median values: 0.168 (IQR 0.140–0.427) vs. 0.140 (IQR 0.140–0.278), (p = 0.177)." (PMID 22808225, 2012). "The values of serpinB4-IgM obtained with SCC103 antibody, which recognises the serpin-protease complex, were slightly lower in patients with HCC, compared to patients with cirrhosis (median values: 0.140 (IQR 0.140–0.278) vs 0.168 (IQR 0.140–0.427 p = 0.177)." (PMID 22808225, 2012). "A trend toward decreasing serpinB4-IgM/serpinB3-IgM median ratio was observed in patients with advanced liver disease, being 1.08 in patients with HCC, 1.10 in patients with cirrhosis and 1.40 in patients with chronic hepatitis (p = 0.079)." (PMID 22808225, 2012). "In patients with chronic hepatitis the serpinB4-IgM(SCC103)/serpinB3-IgM median ratio was 1.40 (range 1.0–4.5), in patients with cirrhosis it was 1.10 (range 0.9–6.2), and in patients with HCC it was 1.08 (range 0.4–4.2)." (PMID 22808225, 2012).
eczema (2 papers, 2017 to 2020). "SerpinB3 and serpinB4 were upregulated in affected skin of eczema patients and in the airway epithelia of patients with allergic asthma, induced via a pathway involving the Th2 cytokines IL-4 and IL-1347–49." (PMID 29051540, 2017).
adenocarcinoma of the lung (1 paper, 2025). "As well, recent evidence suggests that elevated expression of SERPINB3 together with SERPINB4 is not limited to cancers of squamous origin but also extends to adenocarcinoma of the lung, breast, and pancreas, as well as hepatocellular carcinoma." (PMID 40869249, 2025).
brain tumors (1 paper, 2016). "We show that brain tumors can acquire expression of SERPINB1, SERPINB4, and SERPINB9 as a potential mechanism to resist granzyme-induced cytotoxicity." (PMID 26963506, 2016).
cholesteatoma (1 paper, 2012). A pathologic process characterized by the proliferation of keratinizing squamous epithelium resulting in the accumulation of keratin and cells in the middle ear and/or mastoid. "Real-time PCR of PI3, SPRR1B, LCN2 (lipocalin 2), MMP1, MMP9, MMP10, MMP12, SPP1, GJB2, Bcl-xl (BCL2L1), cIAP2 (BIRC3), S100A7A (koebnerisin), S100A9, SERPINB3, CEACAM6, KRT6B and SERPINB4 revealed that the expression levels of these proteins were higher in cholesteatoma than in external canal skin." (PMID 23285167, 2012).
cystic fibrosis (1 paper, 2012). Autosomal recessive disorder caused by pathogenic variants in the CFTR gene (cystic fibrosis transmembrane conductance regulator), which encodes a chloride and bicarbonate channel expressed in epithelial cells, and follow the diagnosis criteria. "Both SERPINB4 and CTSC are up-regulated in IL13 treated human primary bronchial epithelial cells on air liquid interface culture, and PLA2G4A is more active in bronchial explants from individuals with cystic fibrosis." (PMID 22676183, 2012).
glioblastoma (1 paper, 2018). The most malignant astrocytic tumor (WHO grade IV). "Another novel finding of our study is that silencing TRAF3IP2 inhibits the expression of both SERPINB4 and SERPIN2 in the U87 glioblastoma cell line." (PMID 30038719, 2018).
hepatoblastoma (1 paper, 2021). Hepatoblastoma (HB) is a malignant hepatic tumor and is the most common pediatric liver cancer. "Concurrently, the serine/cysteine protease inhibitor SERPINB3, which is directly manipulated by SERPINB4, is modulated by hypoxia through the hypoxia-inducible factor-2α (HIF-2α), and has been recently proven to be upregulated in human hepatoblastoma." (PMID 34069906, 2021).
Insulin resistance (1 paper, 2024). Increased resistance towards insulin, that is, diminished effectiveness of insulin in reducing blood glucose levels. "This also allowed us to highlight examples of genes that were consistently regulated across all four cell types, at both the transcript and protein level, in response to insulin resistance (e.g., SERPINB4)." (PMID 39562547, 2024).
nasal polyps (1 paper, 2024). "Using the Metascape platform, we matched DEGs with the target genes of diseases in the DisGeNET database and found that both DEGs of SerpinB3 and SerpinB4 were associated with nasal polyps and inflammation." (PMID 38550710, 2024).
oral candidiasis (1 paper, 2022). Infection of the mucosal lining of the mouth with the fungus Candida albicans. "Also, the expression of MMP1, MMP10, COL5A2, SERPINB4, and CRABP2 was increased under both conditions, confirming that oral candidiasis may drive OSCC progression events in vivo." (PMID 35089096, 2022).
primitive neuroectodermal tumor (1 paper, 2023). A malignant neoplasm that originates in the neuroectoderm. "In MB and in primitive neuroectodermal tumors (PNET), the granzyme inhibitors SERPINB1 and SERPINB4 were acquired in 23% and 50% of the MB, respectively, while PNETs expressed SERPINB9, SERPINB1, and SERPINB4 in 29%, 29%, and 57% of the tumors." (PMID 37509316, 2023).
prurigo (1 paper, 2025). A name applied to several itchy skin eruptions of unknown cause. "Interestingly, among AD subtypes, serum SERPINB4 expression in the prurigo type was lower than that in the erythroderma type and widespread type." (PMID 40995892, 2025).
skin inflammation (1 paper, 2024). "SERPINB4 and SERPINB3 were also significantly upregulated [log2 (fold change) of 4.09 and 3.21], respectively) and are known to be correlated with AD severity and are increasingly recognized as a biomarker in skin inflammation." (PMID 38344408, 2024).